TERB1 (telomere repeat binding bouquet formation protein 1)
Description:
Meiosis-specific telomere-associated protein involved in meiotic telomere attachment to the nucleus inner membrane, a crucial step for homologous pairing and synapsis. Component of the MAJIN-TERB1-TERB2 complex, which promotes telomere cap exchange by mediating attachment of telomeric DNA to the inner nuclear membrane and replacement of the protective cap of telomeric chromosomes: in early meiosis, the MAJIN-TERB1-TERB2 complex associates with telomeric DNA and the shelterin/telosome complex. During prophase, the complex matures and promotes release of the shelterin/telosome complex from telomeric DNA. In the MAJIN-TERB1-TERB2 complex, TERB1 probably mediates association with the shelterin/telosome complex via interaction with TERF1, promoting priming telomeric DNA attachment'. Promotes telomere association with the nuclear envelope and deposition of the SUN-KASH/LINC complex. Also recruits cohesin to telomeres to develop structural rigidity.
Synonyms: CCDC79; FLJ35894; SPGF60
Tractability: No criterion of Open Targets' tractability assessment is met for any kind of drug.
Gene: Protein-coding gene on chromosome 16 (66,754,640 to 66,801,620, reverse strand). Ensembl gene ENSG00000249961.
Subcellular location: Chromosome, telomere; Nucleus inner membrane
Subcellular location (Human Protein Atlas): Nucleoplasm; Cell Junctions; Cytosol
Gene Ontology:
Molecular function: protein binding
Biological process: homologous chromosome pairing at meiosis; meiotic attachment of telomere to nuclear envelope; meiotic telomere clustering
Cellular component: nuclear envelope; chromosome, telomeric region; nuclear inner membrane; shelterin complex
Genetic constraint (gnomAD): Loss-of-function variants: 37 observed, 45.29 expected, observed/expected ratio (o/e) 0.82, 90% interval 0.63 to 1.08. The upper end of that interval is the gene's LOEUF score, 1.08, which puts it in group 4 of 6, group 1 being the genes least tolerant of losing a copy. Missense variants: 433 observed, 544.77 expected, observed/expected ratio (o/e) 0.79, 90% interval 0.73 to 0.86. Synonymous variants: 156 observed, 186.19 expected, observed/expected ratio (o/e) 0.84, 90% interval 0.74 to 0.96.
Homologues: Orthologues: chimpanzee TERB1 (99% identical), macaque TERB1 (96% identical), dog TERB1 (85% identical), pig TERB1 (84% identical), rabbit TERB1 (81% identical), guinea pig TERB1 (78% identical), mouse Terb1 (71% identical), rat Terb1 (70% identical), tropical clawed frog terb1 (45% identical), zebrafish terb1 (37% identical).
Diseases named in the same sentence as TERB1 in open-access papers:
TERB1 is named in the same sentence as 5 diseases in open-access papers, as found by Europe PMC text mining. Sharing a sentence is not in itself a finding about the gene and the disease. The quoted sentences say what the papers report.
infertile (6 papers, 2014 to 2025). "In humans, biallelic mutations in MAJIN have been reported in infertile males and those in KASH5 and TERB1 in infertile males and in females with POI." (PMID 39545410, 2024). "Accordingly, deletion of any of these genes (i.e., Terb1, Terb2, Majin, Sun1, or Kash5) results in complete infertility in mice in both sexes." (PMID 35081355, 2022). "It has been demonstrated previously that disruption of Terb1 in the mouse results in meiotic arrest and impairment of homologous pairing and synapsis, ultimately resulting in infertility in both males and females." (PMID 35342767, 2022). "TERB1 gene trap mice, which lack TERB1 expression (Terb1-KO), develop normally, but, as in the case of Sun1-KO, are completely infertile." (PMID 24870409, 2014). "Although it is not known whether the remaining genes may lead to female infertility, it is noteworthy that in seven of them (ADAD2, AR, C1orf146, MLH3, RAD21L1, SYCP3, and TERB1), the corresponding female KO mice are infertile." (PMID 40896145, 2025).
male infertility (4 papers, 2020 to 2024). The inability of the male to effect fertilization of an ovum after a specified period of unprotected intercourse. "The male infertility-related variants identified in SPATA3, TTC21A, TERB1, HYDIN, and CCDC155 can be considered additional examples." (PMID 37644014, 2023). "The main goal of this work was exploring the effects of missense mutations on meiotic telomere complex proteins (TERB1, TERB2, and MAJIN) related to male infertility." (PMID 35342767, 2022). "Furthermore, disruption or mutations of any of the MTC genes (TERB1, TERB2, and MAJIN) alters telomere association with the nuclear envelope leading to impairment of homologous pairing and synapsis, a meiotic arrest, and consequently to male infertility." (PMID 35342767, 2022). "We have also identified putatively causal variants in seven genes validated as aetiological factors of male infertility, such as SPAG17, REC114, TERB1, DNAH6, ADGRG2, MAMLD1, and USP26." (PMID 39678461, 2024).
sterility (1 paper, 2022). "Five genes (Tsga10, Terb1, Stra8, Tex14, and Spam1) were predicted to be associated with sterility in male and female Mule ducks." (PMID 36386800, 2022).
TERB1 also shares sentences with these, for which no sentence is quoted: female infertility (2 papers); cancer (1).